GINS3 (GINS complex subunit 3)
Description:
Required for correct functioning of the GINS complex, a complex that plays an essential role in the initiation of DNA replication, and progression of DNA replication forks. GINS complex is a core component of CDC45-MCM-GINS (CMG) helicase, the molecular machine that unwinds template DNA during replication, and around which the replisome is built.
Synonyms: PSF3; FLJ13912; MGORS9
Tractability: Small molecule: a structure with a bound ligand is known. PROTAC: ubiquitination databases record sites on it.
Gene: Protein-coding gene on chromosome 16 (58,295,080 to 58,406,147, forward strand). Ensembl gene ENSG00000181938.
Subcellular location: Nucleus; Chromosome
Subcellular location (Human Protein Atlas): Nucleoplasm
Pathways (Reactome):
DNA Replication: Unwinding of DNA
Gene Ontology:
Molecular function: protein binding
Biological process: DNA replication; DNA replication initiation
Cellular component: CMG complex; GINS complex; nucleoplasm; nucleus; chromosome
Genetic constraint (gnomAD): Loss-of-function variants: 16 observed, 18.19 expected, observed/expected ratio (o/e) 0.88, 90% interval 0.6 to 1.34. The upper end of that interval is the gene's LOEUF score, 1.34, which puts it in group 5 of 6, group 1 being the genes least tolerant of losing a copy. Missense variants: 248 observed, 285.16 expected, observed/expected ratio (o/e) 0.87, 90% interval 0.78 to 0.97. Synonymous variants: 108 observed, 113.59 expected, observed/expected ratio (o/e) 0.95, 90% interval 0.81 to 1.12.
Homologues: Orthologues: chimpanzee GINS3 (99% identical), macaque GINS3 (99% identical), dog GINS3 (94% identical), pig GINS3 (94% identical), guinea pig GINS3 (93% identical), rabbit GINS3 (90% identical), rat Gins3 (90% identical), mouse Gins3 (89% identical), tropical clawed frog gins3 (72% identical), zebrafish gins3 (66% identical), Drosophila melanogaster Psf3 (26% identical), Caenorhabditis elegans psf-3 (22% identical).
Diseases named in the same sentence as GINS3 in open-access papers:
GINS3 is named in the same sentence as 26 diseases in open-access papers, as found by Europe PMC text mining. Sharing a sentence is not in itself a finding about the gene and the disease. The quoted sentences say what the papers report.
lung carcinoma (4 papers, 2013 to 2019). "Restoration of SIX3 in lung cancer cells lacking endogenous SIX3 suppressed cell proliferation and migration, and downregulated a number of genes involved in proliferation and metastasis such as S100P, TGFB3, GINS3 and BAG1." (PMID 23977152, 2013).
sarcoma (3 papers, 2022 to 2024). A usually aggressive malignant neoplasm of the soft tissue or bone. "Using the GEPIA dataset, we compared the expression of GINS mRNAs in sarcoma and normal tissues, it indicated that the expression levels of GINS1, GINS2 and GINS3 in sarcoma were statistically higher than in normal samples." (PMID 35896011, 2022). "Herein, we revealed that GINS3 mRNA transcription was significantly elevated in sarcoma tissues and cell lines." (PMID 36092720, 2022). "These are consistent with our study, in human sarcoma, GINS3 may be a potential biomarker and its expression have influence on the prognosis." (PMID 35896011, 2022). "The GEPIA and Kaplan-Meier Plotter was used to make the investigation of the prognostic ability of GINS1, GINS2, GINS3 and GINS4 expression levels in sarcoma." (PMID 35896011, 2022). "In addition, the mRNA expression levels of the four GINS family members (GINS1, GINS2, GINS3, GINS4) were all higher in sarcoma tissue." (PMID 38473259, 2024). "By interrogating CCLE, we detected the transcription level of GINS members in many types of cancer cell lines, and got the conclusion that GINS1, GINS2 GINS3 and GINS4 were highly expressed in sarcoma cell lines including Ewing's sarcoma, osteosarcoma and chondrosarcoma." (PMID 35896011, 2022). "The prognostic relevance tested was also obvious, increased expression of GINS1, GINS2, GINS3 and GINS4 may provide us new therapeutic targets for the treatment of sarcoma." (PMID 35896011, 2022). "Furthermore, increased GINS3 expression correlated with a shorter OS and DFS in sarcomas." (PMID 36092720, 2022).
glioma (2 papers, 2019 to 2024). A benign or malignant brain and spinal cord tumor that arises from glial cells (astrocytes, oligodendrocytes, ependymal cells). "GINS3 exhibits high expression in numerous tumor tissues, including glioma, and is associated with the development and prognosis of human cancers." (PMID 38584840, 2024).
craniosynostosis (1 paper, 2023). Craniosynostosis is defined as the premature fusion of one or more cranial sutures leading to secondary distortion of skull shape resulting in skull deformities with a variable presentation. "As the number of genes associated with MGORS increases, we see the appearance of subtypes, notably the prevalence of craniosynostosis in CDC45-associated MGORS and neutropenia in GINS3-associated MGORS." (PMID 37059840, 2023).
endometrial cancer (1 paper, 2023). Primary or metastatic malignant neoplasm involving the endometrium (mucous membrane that lines the endometrial cavity). "Previous studies have suggested that GINS3 may play a role in endometrial cancer." (PMID 37780629, 2023).
Failure to thrive (1 paper, 2022). Failure to thrive (FTT) refers to a child whose physical growth is substantially below the norm. "Nevertheless, one possibility is that human cells harboring GINS3 variants might be prone to senescence and reduce overall cell proliferation during development, leading to the failure to thrive that is often observed in MGS patients." (PMID 35603789, 2022).
Meier-Gorlin syndrome (1 paper, 2022). "Here, we report the identification of 7 individuals from 5 unrelated families presenting with a Meier-Gorlin syndrome–like (MGS-like) phenotype associated with hypomorphic variants of GINS3, a gene not previously associated with this syndrome." (PMID 35603789, 2022).
neutropenia (1 paper, 2023). A decrease in the number of neutrophils found in the blood. "Given the unique overlap of MGORS and neutropenia in GINS3 individuals, these features could be used diagnostically as differentials in candidate gene testing." (PMID 37059840, 2023). "Neutropenia has not been described as a common feature associated with any other MGORS gene before, with GINS3 being the first description of such an overlap." (PMID 37059840, 2023). "However, neutropenia is commonly associated with variants in other GINS subunits, GINS1 and GINS4, and in at least some individuals with a biallelic variant in the functionally related subunit of the MCM complex, MCM4, but not GINS2, GINS3 or MCM3, MCM5 or MCM7." (PMID 37059840, 2023).
tumor (12 papers, 2014 to 2024). "Among them, GINS3 was characterized by high tumor purity, immune-desert, activation of EGFR and ephrin receptors, chromosomal instability, fewer KRAS mutations, SMOC1 methylation, immunotherapeutic resistance, and high sensitivity to cetuximab and bevacizumab." (PMID 38429655, 2024). "GINS3 was positive correlated with tumor purity (r = 0.102, p = 1.11e-01)." (PMID 36092720, 2022). "GINS3, a KRAS-inactivated subtype, was featured by high tumor purity, immune-desert, activation of EGFR and ephrin receptors, CIN, fewer KRAS mutations, and SMOC1 methylation." (PMID 36345721, 2022). "Subtypes with rich stromal components (e.g. GINS2 and GINS4) in human CRC samples were inclined to transform into subtypes with high tumor purity (e.g. GINS1 and GINS3) in corresponding PDX derivatives." (PMID 36345721, 2022). "Consistent with the ONCOMINE analysis, all four GINS genes were up-regulated in tumor samples of HCC from TCGA database with 6.382, 3.789, 2.442, and 2.770-fold elevation for GINS1, GINS2, GINS3, and GINS4 mRNA expressions, respectively (P<0.001 for all)." (PMID 30413605, 2018). "In addition, we assessed the expression of molecules such as ANKRD22, GINS3, POLE2, PLEK2, FERMT1 and METTL14 in subcutaneous tumours and lung metastatic tissues." (PMID 39021049, 2024).
cancer (7 papers, 2013 to 2024). A tumor composed of atypical neoplastic, often pleomorphic cells that invade other tissues. "The aberrant expression of other members of GINS (GINS1, GINS2, and GINS3) occurs in different types of human cancers." (PMID 37508549, 2023). "TGFB3, GINS3 and BAG1 have also been reported to be involved in cancer cell proliferation and invasion." (PMID 23977152, 2013).
infection (1 paper, 2025). The state of being infected such as from the introduction of a foreign agent such as serum, vaccine, antigenic substance or organism. "We hypothesize that targets identified in our iPOND analysis, such as GINS3, TOP2A and XRCC1, may play a role in maintaining host replisome stability as wtAAV2 mono-infection progresses long-term." (PMID 40825038, 2025).
GINS3 also shares sentences with these, for which no sentence is quoted: lung adenocarcinoma (4 papers); colorectal cancer (2); adenocarcinoma (1); bladder cancer (1); chondrosarcoma (1); colon carcinoma (1); Ewing sarcoma (1); glioblastoma (1); intrahepatic cholangiocarcinoma (1); liver cancer (1); lung squamous cell carcinoma (1); lymph node metastasis (1); non-small cell lung carcinoma (1); osteosarcoma (1); primordial dwarfism (1).